IL6 (interleukin 6)
Diseases named in the same sentence as IL6 in open-access papers (continued):
Sharing a sentence is not in itself a finding about the gene and the disease.
atherosclerosis (continued). "The recombinant IL-6 aggravates atherosclerosis in apoE-/- mice and inhibition of IL-6 trans-signaling reduces atherosclerosis whereas other studies show atheroprotective properties of IL-6." (PMID 29329335, 2018). "Increased levels of various inflammatory factors in the circulation that play a critical role in the pathogenesis of atherosclerosis, including IL-1β, IL-6, MCP-1 and TNF-α, were detected." (PMID 30413028, 2018). "Elevated levels of serum interleukin-6 (IL-6) and tumour necrosis factor-α (TNF-α), as inflammation mediators, are closely linked to atherosclerosis." (PMID 30526612, 2018). "Injection of IL-6 itself accelerated atherosclerosis in apolipoprotein E-null mice and C57Bl/6 mice either." (PMID 29312959, 2017). "Leptin also stimulates the secretion of inflammatory markers such as CRP, TNF-α and IL-6, which are directly involved in the development of endothelial dysfunction and atherosclerosis." (PMID 27598978, 2017). "IL-6 levels are increased in cardiovascular disease, including atherosclerosis and hypertension, where IL-6 is thought to promote alterations in vascular function and structure." (PMID 29186034, 2017). "In order to study the functional effect of irradiation on inflammatory processes in ECs, we focused on 3 pro-inflammatory cytokines known to be involved in atherosclerosis: IL-6, IL-8, and CCL2." (PMID 28993729, 2017). "Current exerkine targets for atherosclerosis should include irisin, adiponectin, IL-6, and IL-1ra, among others, as they have the most promising results." (PMID 28608819, 2017). "To block the effect of IL-6 on the development of atherosclerosis, we used anti-mouse IL-6 receptor antibody (MR16-1)." (PMID 29312959, 2017). "The potential mechanism for the association between IL-6-572C/G and CHD was not well known, but studies have indicated that inflammation plays an important role in the progression of atherosclerosis." (PMID 29108239, 2017). "Some studies showed increased levels of IL-6 in SLE patients and the association with the burden of atherosclerosis." (PMID 29430084, 2017). "Interleukin-6 is an upstream inflammatory cytokine key player, propagating the downstream inflammatory response in atherosclerosis." (PMID 29312959, 2017). "To confirm the induction of inflammation in irradiated TICAE cells, we focused on two pro-inflammatory cytokines involved in atherosclerosis: IL6 and CCL2." (PMID 28487652, 2017). "Additionally, cardiovascular diseases associated with increases in IL-6, such as atherosclerosis and hypertension, are also associated with oxidative stress, particularly increases in vascular superoxide, suggesting a potential relationship between superoxide, IL-6 and arterial pressure." (PMID 29186034, 2017). "Several studies indicated that IL-6 has critical pathophysiological roles in cardiovascular diseases, such as atherosclerosis and congestive heart failure." (PMID 28531207, 2017). "Among PAF-induced cytokines, IL-6 contributes to atherosclerosis, since a moderate but sustained elevation of serum IL-6 levels correlates with an increased risk in coronary heart disease." (PMID 28686728, 2017). "Among a number of proinflammatory cytokines, IL-6 was not only an important contributor of the pathogenesis of atherosclerosis, but also a valuable indicator of the atherogenesis and instability of atherosclerotic plaques." (PMID 27034587, 2016). "The top pathways included growth hormone signaling, IL-9 signaling, atherosclerosis, and IL-6 signaling." (PMID 27955697, 2016). "In a study conducted on atherosclerosis, IL-6 has been shown to play a pathophysiological role altering lipoprotein lipase (LPL) activity and stimulating lipolysis." (PMID 27413547, 2016).
atherosclerosis (continued). "The main canonical pathways affected were atherosclerosis signaling (p = 3.2E−07), T helper cell differentiation (p = 6.6E−04), IL-6 signaling (p = 2.1E−03)." (PMID 26861446, 2016). "As IL-6 is a known mediator of both atherosclerosis and RA, our data suggest a potential role for this pro-inflammatory cytokine in our model." (PMID 27287704, 2016). "Vascular inflammation is recognized as the foundation mechanism of atherosclerosis, and proinflammatory mediators including IL-6, TNF-α, and MMP-9 play a pivotal role in atherosclerosis." (PMID 27403152, 2016). "Treatment with recombinant IL-6 in atherosclerosis-prone ApoE−/− mice resulted in aggravated atherosclerotic state which was accompanied by increased levels of other pro-inflammatory cytokines and APPs." (PMID 27166190, 2016). "In high fat diet-induced atherosclerosis in rabbits, high levels of IL-6 and fibrinogen were detected in the plasma." (PMID 27594807, 2016). "Here, we observed that PIAS3 levels are reduced in atherosclerotic lesions and that PIAS3 expression decreases in conjunction with increases in interleukin-6 expression and atherosclerosis severity." (PMID 27845432, 2016). "The importance of IL-6 transsignaling is illustrated by an experimental model where IL-6 transsignaling was selectively blocked with the fusion protein sgp130Fc and resulted in regression of atherosclerosis." (PMID 27936014, 2016). "Suppression of IL-6 expression is believed to play an important role in preventing further development of atherosclerosis." (PMID 27799085, 2016). "It is suggested that IL-6 can lead to a decrease of eNOS expression and contributes to the attenuation of NO production and the progression of atherosclerosis." (PMID 27396399, 2016). "Recently, a novel therapeutic reagent targeting IL-6 signaling is under the clinical trial for the treatment of chronic inflammatory diseases including atherosclerosis." (PMID 27034587, 2016). "Inflammation is an important risk factor for atherosclerosis and EAT secretes various cytokines including IL-1β, IL-6, and TNF-α, the levels of which were significantly higher in patients with coronary artery disease." (PMID 25887962, 2015). "The aim of this study was to evaluate the consequences of the coexistence of OSA and HTN on a marker of carotid atherosclerosis (such as IMT) and on inflammatory markers of atherosclerosis (such as IL-6 and PTX-3)." (PMID 26697221, 2015). "Atherosclerosis is a hyperlipidemia-induced chronic inflammatory process of the arterial wall, involving interleukins (ILs) such as IL-1β, IL-6, tumor necrosis factor (TNF)-α, and C-reactive protein (CRP)." (PMID 25664324, 2015). "Blocking IL-6 effects using neutralizing monoclonal antibodies to treat atherosclerosis is controversial." (PMID 26578976, 2015). "Cytokines such as IL-1β, IL-18, IL-6 and TNF-α are key mediators in chronic vascular inflammatory response underlying several aspects of atherosclerosis and cardiovascular disease." (PMID 26600018, 2015). "There were no positive correlations of the other inflammatory markers evaluated (TNF-α, IL-6, IL-1β, homocysteine, hsCRP) in relation to the imaging markers of subclinical atherosclerosis." (PMID 26382922, 2015). "It was reported that the inflammatory responses mediated by cytokines, including MCP-1, IL-6 and sCD40L, were important in atherosclerosis." (PMID 26095681, 2015). "As an important cytokine in the progression of AS, IL-6 was recently found to be positively correlated with atherosclerosis." (PMID 26557859, 2015). "In the SMART study, a study aimed to investigate the benefit of a CD4 guided approach on treatment, markers of inflammation and coagulation such as IL-6, D-dimer and sCD14 were shown to be excellent predictors of atherosclerosis and mortality." (PMID 25814984, 2015). "To date, several studies evaluated blood levels of two important inflammatory markers for atherosclerosis, such as IL-6 and PTX-3, among patients with HTN or OSA alone." (PMID 26697221, 2015).
atherosclerosis (continued). "OSA and HTN have an additive role in the progression of carotid atherosclerosis and in blood levels of inflammatory markers for atherosclerosis, such as interleukin-6 and pentraxin-3." (PMID 26697221, 2015). "With regard to interleukin-6, there is evidence that it is a proinflammatory cytokine which plays an important role in the pathogenesis of atherosclerosis." (PMID 26697221, 2015). "Blocking renin-angiotensin system (RAAS) with an inhibitor of angiotensin converting enzyme (ACE) reduced IL-6 and inflammation markers in atherosclerosis experimental model." (PMID 26578976, 2015). "IL-6 is an inflammatory cytokine of circulation, the levels of which were shown to reactively rise with coronary heart disease; in addition, the IL-6 pathway was suggested to have a role in the process of atherosclerosis." (PMID 26095681, 2015). "IL-6 has been shown to be an inflammation-related growth promoter in many different cancer growth processes, but also in processes such as atherosclerosis and autoimmune disease." (PMID 26079381, 2015). "GlycA concentrations were associated with known inflammatory markers, such as CRP, interleukin-6 (IL-6) and fibrinogen in 5,537 participants of the Multi-Ethnic Study of Atherosclerosis." (PMID 25956924, 2015). "Macrophages produce abundant amounts of pro-inflammatory cytokines, such as TNF-α, IL-6, and IL-1β, to promote atherosclerosis." (PMID 26045945, 2015). "Our finding is consistent with previous studies, supporting the essential role of IL-6 in the pathogenesis of atherosclerosis." (PMID 26075620, 2015). "Inflammation plays a critical role in the risk for and progression of CVD such that inflammatory biomarkers like CRP and IL-6 are generally recognized as independent predictors of atherosclerosis." (PMID 26080804, 2015). "Simultaneously, its activation also has a crucial role in the initiation and propagation of the inflammatory response during atherosclerosis by the production of inflammatory cytokines, such as interleukin-6 (IL-6) and nitric oxide (NO)." (PMID 26492242, 2015). "Atherosclerosis induced by a high-fat diet was characterized by a gradual increase in the levels of the inflammatory cytokines IL-1β, IL-6, MCP-1 and TNF-α compared with the control group." (PMID 25120600, 2014). "HMG-CoA reductase inhibitors (statins) were shown to regulate the expression of chemokines and cytokines such as MCP-1 and IL-6 hence controlling the migration of leukocytes to sub-endothelial sites of inflammation, thereby favorably affecting atherosclerosis." (PMID 25474287, 2014). "The aims of this study were thus to evaluate levels of inflammatory markers of atherosclerosis, such as IL-6, TNF-α, CRP, and PTX-3 in a sample of OSA patients; to assess the correlation between carotid IMT and levels of these inflammatory markers." (PMID 24481114, 2014). "The IL-6-gp130 axis is a key regulator of inflammatory acute phase signaling in hepatocytes for the development of atherosclerosis." (PMID 25318463, 2014). "Hyperproduction of inflammatory markers such as C-reactive protein, interleukin-1 (IL-1), interleukin-6 (IL-6) and tumour necrosis factor-α (TNF-α) can be considered risk factors and some are directly related to the severity of atherosclerosis." (PMID 24642982, 2014). "Interleukin-6 is a proinflammatory cytokine which has an important role in the pathogenesis of atherosclerosis." (PMID 24481114, 2014). "Studies demonstrated that increased serum levels of C-reactive protein (CRP), interleukin (IL)-6, tumor necrosis factor (TNF)-α, and pentraxin (PTX)-3 are important risk factors for atherosclerosis, and cardiovascular diseases." (PMID 24481114, 2014). "By producing pro-inflammatory factors such as TNFα and IL-6, M1 macrophages are able to drive the inflammatory reaction and thereby enhance the development of atherosclerosis." (PMID 25347070, 2014).
atherosclerosis (continued). "For example, in subclinical atherosclerosis patients, levels of IL-6 are correlated with decreases in naive CD4+ T cells." (PMID 25244034, 2014). "It is able to reduce serum levels of TNFα and IL6 and plays a protective role against atherosclerosis." (PMID 25136143, 2014). "We demonstrated that elevation of APN levels suppressed aortic expression of key inflammatory genes (TNF-α, IL-6, IL-12) in a hypertensive, pro-inflammatory and hyperlipidemic model of atherosclerosis." (PMID 24466075, 2014). "In atherosclerosis, LTB4 can induce the overexpression of TNF-α, IL-6 and MCP-1 mRNA in cultured monocytes, causing an inflammatory environment." (PMID 25229347, 2014). "Since our main objective was to associate the membrane expression of CD36 with subclinical atherosclerosis, other molecules related with cardiovascular risk such as ox-LDL, IL-6, and TNFα were tested.Results." (PMID 25006585, 2014). "Cytokines, such as TNF-α and IL-6, are primarily involved in the early stages of the inflammatory response culminating in atherosclerosis." (PMID 24741576, 2014). "Levels of anti-EPC antibodies were determined in 100 subjects and differential risk score for atherosclerosis, as well as to circulating EPC levels and the inflammatory markers IL-6 and C-reactive protein." (PMID 24945945, 2014). "Emerging data suggest that the proinflammatory cytokine IL-6, secreted by adipocytes, plays an important role in atherosclerosis." (PMID 25215291, 2014). "IL-6 is involved in the development of atherosclerosis, myocardial remodeling, and experimental and clinical cardiac dysfunction." (PMID 24086665, 2013). "Inflammatory molecules such as MCP-1, IL-6, VEGF, and IL-8 have been implicated in atherosclerosis; however, their regulation and expression by adventitial fibroblasts remain to be fully defined." (PMID 24307759, 2013). "PPAR-γ controls the expression of paraoxonase that are shown to decrease inflammatory factors involved in the development of atherosclerosis (such as IL-1, IL-6 and TNF-α)." (PMID 23437105, 2013). "Eventually upon upregulation of the key transcription factor NFκB, interleukins (IL-6 and IL-8) and gelatinolytic enzymes like metalloproteinases (MMPs) and others are synthesized, all known to play a role in atherosclerosis development." (PMID 24077237, 2013). "Clinically, the reduction of CRP-induced IL-6 production with E2 pre-treatment shown by our result could indicate a key role of this hormone in the prevention or reduction of cytokine inflammatory response implicated in the development and maintenance of atherosclerosis." (PMID 23111890, 2013). "Adipocytokines such as interleukin-6 (IL-6) and adiponectin as well as inflammatory cytokines such as C-reactive protein (CRP) are associated with the development of atherosclerosis and type 2 diabetes in adults." (PMID 23984329, 2013). "Various cytokines and inflammatory mediators (IFN-γ, IL-1, IL-6, TNFα etc.)contribute to the pathogenesis of inflammation observed in atherosclerosis." (PMID 23305356, 2013). "The results of previous studies have demonstrated that hs-CRP, TNF-α and IL-6 levels correlate with coronary heart disease, myocardial depression, atherosclerosis, left ventricular dysfunction and other factors." (PMID 24137221, 2013). "Levels of HSP70, bone morphogenetic protein-4, and IL-6 were all elevated within the aortic wall as well as the serum in a mouse model of atherosclerosis." (PMID 23304456, 2012). "Untreated HIV infection is characterized by increased levels of pro-inflammatory cytokines such as IL-6 and hsCRP, and increased expression of adhesion molecules, factors identified to be important in the pathogenesis of atherosclerosis." (PMID 22970224, 2012). "IL-6 also stimulates the synthesis of CRP, which is well known as both a marker and important risk factor of atherosclerosis in the general population and CKD patients." (PMID 22567283, 2012).
atherosclerosis (continued). "In all pGDM women, sE-selectin, sICAM-1, interleukin-6, and hsCRP values were significantly associated with IMT, thus supporting associations of these biomarkers with pathogenesis of atherosclerosis." (PMID 22577379, 2012). "Low levels of adiponectin are associated with higher levels of highly-sensitive C-reactive protein (hs-CRP) and IL-6, two inflammatory mediators that are involved in the initiation and progression of atherosclerosis and renal disease." (PMID 22567283, 2012). "diHPA exerted anti-inflammatory properties by reducing the secretion of pro-inflammatory cytokines, TNF-α, IL-1β and IL-6, involved in the early stages of atherosclerosis from lipopolysaccharide (LPS)-stimulated human peripheral blood mononuclear cells (PBMC)." (PMID 21272305, 2011). "The pro-inflammatory cytokines TNF-α, IL-1β, IL-6, and other acute phase proteins such as serum amyloid A (SAA) and C-reactive protein (CRP) have been associated with atherosclerosis or increased risk of cardiovascular disease." (PMID 21249123, 2011). "In this study, we aimed to investigate the role of ECM in the pathogenesis of atherosclerosis and the potential mechanism of adiponectin upregulating P4Hα expression in IL-6-stimulated HASMCs." (PMID 21829524, 2011). "Our data from this shear stress flow model suggest that mast cell–derived TNF-α and IL6 contribute to leukocyte adhesion during the pathogenesis of atherosclerosis or other vascular diseases." (PMID 21264293, 2011). "The cytokines TNF-α, IL-1β IL-6, and IL-8 are important in vascular inflammation and atherosclerosis." (PMID 21249123, 2011). "In a previous study, we demonstrated the importance of the IL-6-gp130 axis -as a key regulator of inflammatory acute phase signaling in hepatocytes-for the development of atherosclerosis." (PMID 21573245, 2011). "C-Reactive Protein is a marker of inflammation and atherosclerosis regulated by Interleukin-6 (IL-6) and Tumor Necrosis Factor-α (TNF-α), which secretions dose-dependently decreased in presence of vitamin D." (PMID 20937091, 2010). "IL6 is a key mediator of inflammation and it has been demonstrated to play an important role in the pathogenesis of atherosclerosis and vascular diseases." (PMID 20948561, 2010). "Several studies have shown that pro-inflammatory cytokines, such as tumor necrosis factor (TNF)-α, interleukin (IL)-1β, and IL-6, play an important role in the development of atherosclerosis." (PMID 20946675, 2010). "In an analysis of data from nearly 6000 participants in the Multi-Ethnic Study of Atherosclerosis (MESA), consumption of nuts and seeds was inversely associated with levels of inflammatory markers, C-reactive protein (CRP), interleukin-6 (IL-6) and fibrinogen." (PMID 22254047, 2010). "It has been proposed that inflammation is the driving force in atherosclerosis, and strong evidence supports the central role of proinflammatory cytokines, such as interleukin-1β (IL-1β) and interleukin-6 (IL-6) in these pathologies." (PMID 20107610, 2009). "Control subjects were individually matched for degree of atherosclerosis, in addition to age and sex, because each of these variables are known to influence peripheral inflammatory markers, including IL-6 and neopterin." (PMID 17328808, 2007). "Diabetic patients have elevated blood levels of IL-6,which is known to increase the inflammation and the development ofvascular disease and atherosclerosis." (PMID 16864906, 2006). "First, systemic inflammation, as indicated by elevated CRP and IL-6 levels, may promote both venous remodeling and arterial atherosclerosis." (PMID 40912305, 2026). "At the same time, IL-6 triggers the release of IL-1RA and IL-10, which have anti-inflammatory properties and may protect against atherosclerosis." (PMID 39957063, 2025). "IL-6 exacerbates endothelial injury, promoting atherosclerosis in autoimmune conditions." (PMID 41179568, 2025).